SOX2 (SRY-box transcription factor 2)
Diseases named in the same sentence as SOX2 in open-access papers (continued):
Sharing a sentence is not in itself a finding about the gene and the disease.
glioma (continued). "Finally, we also investigated Sox2, an oncogene which plays important roles in cancer stem cells (CSC) and in TMZ-resistance in glioma." (PMID 29348889, 2017). "Moreover, human gliomas display a stemness signature, and SHH-GLI signaling regulates the expression of stemness genes (e.g. Nanog, Oct4, Sox2, CD133) and the self-renewal of CD133(+) glioma cancer stem cells." (PMID 29079783, 2017). "Moreover, DHA exerted a differentiating effect on T269 cells leading to a down-regulation of the stem cell markers Sox2 and nestin which argues again for its use in the combination with TMZ to better target glioma stem cells." (PMID 27447560, 2016). "Thus, cells with elevated SOX2 expression are more resilient to TMZ, whereas its inhibition sensitizes glioma cells to this agent." (PMID 27822457, 2016). "Adult glioma stem cells share the expression of a panel of proteins physiologically present during early embryonic development of the central nervous system, such as CD133, Nestin, SOX-2 and other less well characterized marker proteins." (PMID 27213425, 2016). "Additionally, SHH activated CD133+ glioma cells demonstrated an increased expression pattern of stemness markers like CD133, SOX-2 and Nestin." (PMID 24978848, 2014). "In glioma the intensity and not the frequency of SOX2 expression was shown to be an indicator of a more stem-like phenotype." (PMID 24940116, 2014). "In glioblastoma multiforme, SOX2 down-regulates miR-145, and both are probably involved in a double-negative feedback loop in maintaining the stemness of glioma stem cells." (PMID 23577178, 2013). "In glioblastoma, SOX4 serves as a direct TGF-β target gene, conducts an alternative non-SMAD TGF-β signaling, and induces SOX2 expression to maintain the stemness of glioma-initiating cells." (PMID 23251334, 2012). "Surprisingly, ectopic expression of Sox2 in established glioma cells was not sufficient to support self-renewal, suggesting that additional factors are required." (PMID 22069467, 2011). "Treatment of Sox2-negative glioma cell lines with 5-azacitidine resulted in the re-expression of Sox2 and in a change in the methylation status of the Sox2 promoter." (PMID 22069467, 2011). "We suggest that SOX2 expression in U343-MG and U343-MG glioma cells might inhibit TCF/LEF-signaling in the same way keeping the glioma cells in a more undifferentiated stem cell-like state." (PMID 22070920, 2011). "Taking together, SOX2 could act through SOX1 and SOX18, and thus play roles in both maintaining stem cell properties of glioma cells and forming tumor vasculature in gliomas, which are two major obstacles preventing us from treating these tumors effectively." (PMID 21211035, 2011). "Our data is consistent with the observation that SOX2 is widely expressed in gliomas including glioblastomas but not in normal brains except for in ependymal layers." (PMID 21211035, 2011). "Noteworthy, in our experiments we showed that SOX2 seems not to be fundamental for the maintenance of U343-MG and U373-MG glioma cell proliferation." (PMID 22070920, 2011). "SOX2, a known neural stem/progenitor cell (NSPC) marker, is also expressed in gliomas and GCSCs." (PMID 21600039, 2011). "The generated CTLs efficiently lysed cells of all glioma cell lines, whereas only marginal lysis was observed when the SOX2-negative melanoma cell line 93.04A12.1 expressing HLA-A2 was used as a control." (PMID 17375044, 2007). "When U-87 or U-118 glioma cells were seeded on these scaffolds, they formed compact spheroids and exhibited significantly higher expression of glioma stem cells-related markers, including CD133 and SOX2, along with enhanced levels of EMT genes such as Snail and N-cadherin." (PMID 41149224, 2025). "Therefore, efforts to decrease the expression of SOX2 and increase the expression levels of TET could be used to prevent the occurrence and progression of gliomas." (PMID 40469294, 2025).
glioma (continued). "This ZFHX4/SOX2 regulatory circuit likely serves to amplify and stabilize the pro-malignancy signals initiated by ZFHX4-AS1, effectively “locking” glioma cells into a highly aggressive phenotype and offering a more nuanced understanding of glioma’s relentless progression." (PMID 41458623, 2025). "They analyzed The Glioma French, the Cancer Genome Atlas (TCGA), and the Chinese Glioma Genome Atlas datasets, reporting that the expression of Twist 1 [a gene that stimulates the stemness markers such as BMI1, CRIPTO1, DPPA2, KLF4, and SOX2 in CSC] is related to a poor prognosis in GB patients." (PMID 39153092, 2024). "To explore the role of SOX2 in HCMV infection in gliomas, we first determined whether high SOX2-expressing glioma cells are more permissive to HCMV infection than low SOX2-expressing cells by quantifying HCMV infection in six glioma cell lines with various SOX2 expression levels." (PMID 37058447, 2023). "We obtained glioma stem cells using specific media (DMEM/F12, with 2% B27, 25ng/mL bFGF, 25ng/mL EGF and 1% penicillin/streptomycin) and verified the changes in mRNA levels (CD133 U251 vs. GSCU251: P=0.0005; SOX2 U251 vs. GSCU251P=0.0034) and protein levels of their stem-biological markers." (PMID 36527092, 2022). "Specifically speaking, the stemness-related regulators, CD133, MELK and SOX2 were substantially downregulated following transfection of shCDC42EP3-harboring lentivirus into SHG-44 cells, indicating concurrent reduction in expression of CDC42EP3 and stemness of glioma stem cells." (PMID 35365622, 2022). "The separation of DNA-PK from SOX2 because of DNA double-strand breaks promoted WWP2 binding with SOX2 and failed to stabilize SOX by preventing the ubiquitination and degradation of SOX2 mediated by WWP2, thus promoting the differentiation of glioma stem cells." (PMID 36091384, 2022). "Therefore, according to the literature above, we wondered whether Sox2, Oct4, KLF4, Nanog, Lin28A and Lin28B contribute to glioma cell dedifferentiation in hypoxic environments." (PMID 34976166, 2022). "Thus, the activation of SOX2-dependent transcription creates a unified basis for the processes of intercellular interaction at the level of the FGF and TGF-beta/SMAD signaling pathways during the formation of NS by glioma cells." (PMID 36231068, 2022). "In addition, stem cell markers, such as, SOX2 and Nestin, were also upregulated in GBM-RICCS compared with the control group, suggesting that GBM-RICCS exhibits stem-like characters in glioma cells." (PMID 34831193, 2021). "In addition, we assessed the stemness of glioma cells by measuring a panel of stem cell marker genes using western blotting analysis and observed significantly reduced expression levels of CD133, Nestin, Nanog, and SOX-2 after curcumol treatment." (PMID 34739394, 2021). "Moreover, stem cell markers, such as, SOX2, and Nestin, were upregulated in RICCS, compared with Cont, suggesting that RICCS might exhibit stem-like characters in glioma cells." (PMID 34831193, 2021). "In addition, STAT3 binding to the Notch1 promoter inhibits this signaling pathway and may impede the maintenance of glioma stem-like cells while reducing the expression of glioma stem cell markers CD133, SOX2, and nestin." (PMID 34439159, 2021). "In addition to SOX-2, MALAT1 downregulation has shown inhibitory effects on the expression of Nestin (another stemness marker) and proliferation of glioma stem cell lines by activating the ERK/MAPK signaling pathway, which is a key pathway in tumor development." (PMID 34322395, 2021). "However, inhibition of mTORC1 has also been described to attenuate SOX2 and further downstream SOX9 expression in glioma, and both PI3K inhibitors and rapamycin reported to suppress SOX2-driven tumorigenicity from esophageal squamous cells in a murine xenografts." (PMID 31477842, 2020). "The protein expression of SOX2 in recurent glioma has not been reported." (PMID 31718604, 2019).
glioma (continued). "Glioma CSCs may produce VEGF, promoting vessel growth, while endothelial cells cocultured with glioma CSCs, facilitated the CSC-like phenotype of glioma cells by increasing the expression of Sox2, Olig2 and Bmi1." (PMID 30510501, 2018). "Long-term exposure of glioma cell lines containing small stem cell populations to therapeutic stress (temozolomide) conferred differentiated glioma cells with stemness and pluripotency markers, such as CD133, SOX2, Oct4 and Nestin, whilst also upregulating HIF1/2α expression." (PMID 30510501, 2018). "Interestingly, we observed that specially SOX1 and SOX2 expression was elevated in those cells, suggesting that these members of the SOX family may be mediators of PR-LncRNA activity in gliomas." (PMID 30143669, 2018). "The ability of CAR to interfere with Nanog, Oct4, SOX2, CD44 and BMI1 expression is consistent with the effects of other natural compounds (e.g., adriamycin and diflourinated curcumin) to control the cancer stem cell bulk and the aggressiveness of glioma and pancreatic adenocarcinoma." (PMID 29123181, 2017). "Silencing NRF2 decreases the self-renewal capacity of glioma stem cells by critically reducing the expression of B lymphoma Mo-MLV insertion region 1 homolog (Bmi1, a transcription regulation factor for stem cells), SRY-box 2 (Sox2, a regulator of growth factors) and Cyclin E." (PMID 28671577, 2017). "Moreover, high HMGA2 expression levels correlate with shorter survival time in glioma patients using the CGGA (The Chinese Glioma Genome Atlas) dataset, which is consistent with reports showing higher levels of IL-6/HMGA2/SOX2 expression indicated shorter overall survival period in GBM patients." (PMID 27259253, 2016). "DCA decreased the expression of Taldo, Stat3, Sox2 and Gata6 in glioma spheroids but not in NSCs." (PMID 24481450, 2014). "Since we observed that SOX2 depletion led to a decrease in cyclinD1 expression we suggest that the same mechanism might be involved in the increased RhoA/ROCK2 signaling in U343-MG and U373-MG glioma cells." (PMID 22070920, 2011). "In glial tumors, growth, angiogenesis, and therapeutic resistance itself are supported by glioma stem cells in which hypoxia upregulated the expression of stemness markers (CD133, OCT4, SOX2) and promoted CD133 glycosylation, which may play a role in the hypoxia-mediated anti-apoptosis process." (PMID 35870078, 2022). "To identify novel intermediate regulatory factors between SFRP2 and SOX2 we hypothesized that activity of such genes should increase or decrease upon SFRP2-overexpression but not upon SOX2-overexpression, and correlate with SOX2 expression in the CCLE glioma cell lines." (PMID 34021259, 2021). "Moreover, experiments in vitro revealed that their levels, especially of SOX1 and SOX2, were significantly elevated in PR-LncRNA silencing cells and that knock-down of SOX1 and SOX9 expression dramatically reduced the pro-oncogenic activities promoted by PR-LncRNA silencing in glioma cells." (PMID 30143669, 2018). "Indeed, POU3F2, SOX2, SALL2, and OLIG2 have been shown to be the core set of transcription factors essential for GBM propagation, which are within the set of 19 transcription factors (including SOX1) required for successful reprogramming of differentiated glioma cells into GSCs48." (PMID 28425506, 2017). "This assay showed that SOX2-OE inhibited the promoter activity of PML but not Sp100 in 293T and glioma cells." (PMID 37058447, 2023). "The sole presence of either KRAB or DNMTs fused with SOX2 (both full-length and without C-terminal domain) was not effective in blocking SNB19 glioma cells in vitro; thus, we decided to combine them together." (PMID 35921410, 2022). "In glioma, BTK is considered a cancer cell biomarker, although our data using co-immunofluorescence show that most of the SOX2-positive cancer cells do not express BTK." (PMID 34645618, 2021).
glioma (continued). "Additionally, the stemness marker, CD133, which was significantly upregulated in GBM compared with normal tissues, could well distinguish between different grades of gliomas, while the other upregulated stemness marker, SOX2, was not different for the different grades of glioma." (PMID 34805277, 2021). "Prrx1 potentiated stemness acquisition of non-stem tumor cells (NSTCs) and stemness maintenance of glioma stem cells (GSCs) by upregulating GSC markers including CD133, SOX2, and OCT4." (PMID 34131109, 2021). "However, SOX2 may not be the only critical factor in glioma progression." (PMID 33408794, 2021). "First, primary and lined glioma cells were infected with or without ADV, and the expression of pluripotency factors c-MYC, SOX2, OCT4 and NANOG were determined by RT-qPCR and western blotting." (PMID 32843056, 2020). "Using human glioma-initiating cell (GIC) lines (GIC1 and GIC2) created from anaplastic oligodendroglioma (AO) and GBM, both GIC1 and GIC2 expressed SOX2 and SOX3, and neither GIC line expressed SOX1." (PMID 32388501, 2020). "The negative correlation between AP-2α and Nanog expression, Sox2 expression, CD133 expression, and p-STAT3 expression was further confirmed in glioma tissues and cell lines." (PMID 31534499, 2019). "In our own Chinese glioma collection, we found that expression levels of both LINC00461 and SOX2 mRNAs were markedly higher in gliomas than those in non-neoplastic brain tissues (P < 0.001)." (PMID 29137410, 2017). "Cyclopamine, an inhibitor of the SHH pathway, was also proved effective in reducing SOX2 expression and inducing cytotoxicity in in vitro studies, but unlike rapamycin, its combination with TMZ did not increase the sensitivity of glioma cells to chemotherapy." (PMID 27822457, 2016). "There are also limitations: Although GFAP is a robust glioma marker, it does not label all glioma subpopulations (e.g., GFAP-negative tumor cells), and future work could incorporate additional markers (e.g., Sox2, Olig2)." (PMID 41226489, 2025). "Intriguingly, in adult astrocytic tumours, we previously noticed that the frequency of Sox2/CD44v9-negative and phospho-S6-positive tumour cell populations (differentiated tumour cells), but not Sox2/CD44v9-positive and phospho-S6-negative CSC populations, correlated with the grade of glioma." (PMID 37370764, 2023). "While the mRNA levels of genes related to pluripotency (SOX2, KLF4, MYC and NOTCH1) were not obviously correlated with the clinical glioma grade or outcome, the mRNA level of POU5F1, which also plays a crucial role in PGC specification, was often linked to a higher glioma grade and poor outcome." (PMID 36435765, 2022). "Moreover, GSC exosomes increased Notch-1, as well as stemness-related proteins such as CD133, nestin, octamer-binding transcription factor 4 (Oct4), and SRY-box transcription factor 2 (Sox2), in treated non-CSC glioma cells." (PMID 34638913, 2021). "Mechanistically, we could not detect an influence of TAL1 and SLUG on the two key glioma transcription factors we explored (OLIG2 and SOX2) so their specific downstream targets remain to be fully identified." (PMID 34771555, 2021). "For comparison, in the lower grade glioma, the percentage of BTK and SOX2 co-expression was much higher; however, patient-derived cell models from this lower grade were not available to compare with tissue SOX2 and BTK co-expression." (PMID 34645618, 2021). "LN18 glioma cells grown as non-adherent cells at a low density under serum-free conditions form spheres and display higher expression of stemness markers (NANOG, POU5F1, SOX2 and PROM-1) than adherent LN18 cells." (PMID 33050631, 2020). "Indeed, we do not have complete evidence showing that in gliomas there is an intrinsically heterogeneous CSC-like population with a gradation of CD133, Nestin, and Sox2, but it appears to be plausible." (PMID 29518912, 2018).
glioma (continued). "The isolation and characterization of glioma CSCs is complicated by the absence of universal phenotypic markers, but a number of candidate proteins have been proposed for its role: СD133, CD44, CD49f, Musashi-1, Nestin, Nanog, Oct4 and Sox2." (PMID 31435515, 2018). "Thus, they isolated glioma stem lines growing as floating neurosphere-like aggregates (positive for SOX2 and differentiating to GFAP-positive cells) and other ones growing as irregularly-shaped floating aggregates, with some adherent cells (positive for CD44 and negative for SOX2)." (PMID 30279357, 2018).